RYR3 (ryanodine receptor 3)
Diseases named in the same sentence as RYR3 in open-access papers (continued):
Sharing a sentence is not in itself a finding about the gene and the disease.
amyotrophic lateral sclerosis (1 paper, 2022). Amyotrophic lateral sclerosis (ALS) is a neurodegenerative disease characterized by progressive muscular paralysis reflecting degeneration of motor neurons in the primary motor cortex, corticospinal tracts, brainstem and spinal cord. "Moreover, several potential disease-causing genes were detected and markedly enriched in the pathways of neurodegeneration (including WNT16, RYR3 and RYR1 genes) and amyotrophic lateral sclerosis (ALS, including NUP205, CAPN2, and NUP214 genes)." (PMID 35355568, 2022).
angina (1 paper, 2023). "In the subgroup of patients with a pre‐existing heart disease (MI, angina or HF) at the start of dCCB prescribing, RYR3 TT homozygotes had an increased risk of developing incident heart diseases compared to common CC homozygotes (75.4 vs. 67.8) with a HR 1.25 (95% CI 1.09 to 1.44, P = .002)." (PMID 36134646, 2023).
bladder cancer (1 paper, 2022). "The results showed that TJP1 mRNA levels were positively correlated with TTN and RYR3 mRNA levels in bladder cancer tissues." (PMID 35087173, 2022). "In addition, TJP1 mRNA expression levels were positively correlated with TNT and RYR3 mRNA expression levels in patients with bladder cancer." (PMID 35087173, 2022). "TJP1 mRNA levels were positively correlated with TTN and RYR3 mRNA levels in bladder cancer tissue." (PMID 35087173, 2022).
cholangiocarcinoma (1 paper, 2022). A carcinoma that arises from the intrahepatic biliary tree (intrahepatic cholangiocarcinoma) or from the junction, or adjacent to the junction, of the right and left hepatic ducts (hilar cholangiocarcinoma). "For example, RYR1 in cholangiocarcinoma (CHOL) and RYR3 in testicular germ cell tumors (TGCT) only had missense mutations, and RYR2 in CHOL and RYR3 in thyroid carcinoma (THCA) only had silent mutations." (PMID 36167878, 2022).
chordoma (1 paper, 2023). Chordomas are rare malignant tumors arising from embryonic remnants of the notochord in axial skeleton. "The expression of AMOT, RYR3, P2RX5, and TNFSF14 were higher in recurrent chordomas than primary chordomas while NPTX1 was contrast." (PMID 38012562, 2023). "miR-186-5p, miR-125b-5p, miR-1260a, and their target protein mRNAs including AMOT, NPTX1, RYR3, P2RX5, TNFSF14 may be the basement of chordoma research." (PMID 38012562, 2023).
colon adenocarcinoma (1 paper, 2022). "The average number of RyR2 mutations per person was generally higher than that for RYR1 and RYR3, mostly strikingly in LUAD, LUSC and colon adenocarcinoma (COAD)." (PMID 36167878, 2022).
Encephalopathy (1 paper, 2024). Encephalopathy is a term that means brain disease, damage, or malfunction. "RYR3, known for its role in calcium signaling and synaptic plasticity, and RANBP2, associated with nuclear transport and encephalopathy, may converge in their impact on neural function via shared pathways, such as calcium homeostasis, neuronal signaling, or stress response pathways." (PMID 39509559, 2024).
hepatocellular carcinoma (1 paper, 2025). A malignant tumor that arises from hepatocytes. "For instance, recent studies have identified miRNA binding site polymorphisms in genes implicated in migration, invasion, and angiogenesis, such as RASA1, COL1A2, CA9, CD147, VHL, and RYR3, which can influence susceptibility to hepatocellular carcinoma (HCC)." (PMID 41409896, 2025).
ischemia (1 paper, 2025). A hypoperfusion of the BLOOD through an organ or tissue caused by a PATHOLOGIC CONSTRICTION or obstruction of its BLOOD VESSELS, or an absence of BLOOD CIRCULATION. "Moreover, whereas both the RyR2 and RyR3 isoforms present in rat brain cortices exhibit endogenous levels of S-glutathionylation and S-nitrosylation, ischemia only increases the S-glutathionylation and S-nitrosylation levels of the RyR2 isoform." (PMID 40076722, 2025).
leukemia (1 paper, 2017). A malignant (clonal) hematologic disorder, involving hematopoietic stem cells and characterized by the presence of primitive or atypical myeloid or lymphoid cells in the bone marrow and the blood. "Using RNA sequencing, we found that genes associated with AML subtypes, such as RYR3, RHAG, PCDH9, ANK1, ADAMTS3, and DLC1, were significantly up-regulated in the leukemia cells of two responders, but not in the 3 non-responders." (PMID 28900115, 2017).
motor neuron disorder (1 paper, 2021). Neurological disease involving the motor neuron. "In motor neurons, the RYR3 protein regulates intracellular calcium, in which AMPA-type GluR (glutamate receptor) channels regulate the intracellular calcium homeostasis that is altered in neurodegenerative diseases and can play an important role in the pathogenesis of motor neuron disorders (MND)." (PMID 33557955, 2021).
myotonic syndrome (1 paper, 2014). "RYR3 high ranking is boosted by a strong contribution of calcium homeostasis terms, explaining why RYR3 received a similarly high score in the Myotonic Syndromes and Ion Channel Muscle Diseases groups, which also have a strong component of calcium homeostasis terms." (PMID 25353622, 2014).
nemaline myopathy (1 paper, 2023). Nemaline myopathy (NM) encompasses a large spectrum of myopathies characterized by hypotonia, weakness and depressed or absent deep tendon reflexes, with pathologic evidence of nemaline bodies (rods) on muscle biopsy. "A recent case report has suggested that variants in RYR3 may potentially be linked to nemaline myopathy, but further research is still needed to establish this connection." (PMID 38034995, 2023).
neuroblastoma (1 paper, 2017). Neuroblastoma (NB) is the most common solid, extracranial childhood tumor. "Moreover, expression of crucial regulators of calcium signaling, such as IP3R3, RYR3 and S100A6, are deregulated upon CDDP or TOPO treatment of neuroblastoma cells." (PMID 28206967, 2017). "This was also investigated in IMR-32 cells that confirmed the up-regulation of S100A6; IP3R3 and RYR3 but showed no down-regulation of RYR1 in CDDP treated neuroblastoma cells." (PMID 28206967, 2017).
schizophrenia (1 paper, 2012). A major psychotic disorder characterized by abnormalities in the perception or expression of reality. "RYR3, a brain-specific ryanodine receptor for controlling intracellular calcium concentration, was found to be a susceptible gene for schizophrenia." (PMID 23264780, 2012).
Sinus bradycardia (1 paper, 2021). Bradycardia related to a mean resting sinus rate of less than 50 beats per minute. "Therefore, all three genes DLG2, CATSPERB and RYR3 may not serve as susceptibility genes of sinus bradycardia induced by SGAs." (PMID 33914752, 2021).
tumor (8 papers, 2015 to 2025). "The RYR3 gene encodes a calcium ion channel protein, and mutations in this gene may be linked to the dysregulation of calcium in tumor cells." (PMID 38086955, 2023). "TMB in the tumor tissues with mutated RYR3 (n = 5) was much higher than that in non-mutated RYR3 (n = 38) (p < 0.01)." (PMID 37038181, 2023). "AGBL4, ROBO2, EYS and RYR3 appeared to have two insertions in distinct sites in the same tumour, though these could be insertions at a single rearrangement junction, since this is known to occur." (PMID 26159513, 2015). "On the contrary, the overexpression of genes encoding muscle-like tumor antigens, such as NEFM, HSP60, and RYR3, may be a hallmark of thymic neoplastic tissue, which can predispose to MG in the presence of additional susceptibility molecular/genetic factors (e.g., susceptibility HLA alleles)." (PMID 36979710, 2023). "Therefore, tumor suppressor role of RYR3 on HNSCC still need to be further clarified." (PMID 33737696, 2021). "Conversely, the genes downregulated in the MYB-expressing epithelial clusters were predominantly tumor-suppressive transcriptional signatures, including OCM, IER2, JPH2, RYR3, MYH11and B3GALT1." (PMID 40950184, 2025).
cancer (7 papers, 2018 to 2025). A tumor composed of atypical neoplastic, often pleomorphic cells that invade other tissues. "Although the number of mutations in RYR2 was significantly higher than RYR1 and RYR3, the ratio of mutation categories in most cancer types was relatively consistent." (PMID 36167878, 2022). "Similarly, the mutational status of RYR3 cannot stratify the survival in all cancer types, but can stratify the patient survival in ACC (P = 0.0071) and KIRC (P = 0.0042)." (PMID 36167878, 2022). "To understand the similarities and differences of cancer mutational status across RYR1, RYR2 and RYR3, we further analyzed the average number of mutations of the three RYR isoforms in different cancer types." (PMID 36167878, 2022). "In order to understand the distinct mutational status of each cancer type, we further analyzed the ratio of RYR1, RYR2 and RYR3 mutation types in 30 different cancers." (PMID 36167878, 2022). "To study the mutation profile of RYR in various types of cancers, we first investigated the distribution of mutations by mapping all RYR1, RYR2 and RYR3 mutations from 10,114 cancer patients recorded in the TCGA database." (PMID 36167878, 2022). "The main pathways of methylome biomarkers were associated with calcium signalling (CACNA1E, RYR2, RYR3), cancer pathways (DCC, RASSF1, WNT1, CTNNA2), multiple neurodegenerative diseases (WNT1, DNAI1, RYR2, RYR3), immune system disorders and cell adhesion (HLA-DRA, HLA-DRB1, HLA-DRB5)." (PMID 40524349, 2025). "RYR2 may be more expressed than RYR1 and RYR3 in tissues such as lung and gastrointestinal organs and tract, where the incidence of cancers is high, and this may lead to the identification of more mutations predominantly in RYR2 than RYR1 or RYR3." (PMID 36167878, 2022).
cardiac diseases (2 papers, 2015 to 2023). "RyR3 protein mobilizes stored Ca + 2 in both cardiac and skeletal muscle to initiate muscle contraction and dysregulation of both RyR2 and RyR3 that have been associated with cardiac diseases." (PMID 25750702, 2015).
infection (2 papers, 2015 to 2025). The state of being infected such as from the introduction of a foreign agent such as serum, vaccine, antigenic substance or organism. "This infection upregulated certain gene expressions, such as ATP5PF, ATP6, COX1, MT-ND5, CYTB, and HIF-1α and downregulated CACNA1B and RYR3 expression." (PMID 41157602, 2025).
genetic muscle disease (1 paper, 2024). "We also discovered missense changes in RYR3, a gene that is highly expressed in skeletal muscle but has not yet been linked to a genetic muscle disease." (PMID 39063061, 2024).
myopathy (1 paper, 2024). A disease of the muscle in which the muscle fibers do not function properly. "Our findings provide important evidence for the diagnosis of RYR3-related DEE, and we hypothesize that RYR3 gain-of-function variants resulting in “leaky” Ca2+ release channels may be a molecular genetic feature leading to DEE rather than myopathy." (PMID 39220738, 2024).
neurodevelopmental disorder (1 paper, 2023). A behavioral and cognitive disorder with onset during the developmental period that involves impaired or aberrant development of intellectual, motor, or social functions. "However, a more recent targeted sequencing and integrative analysis study of 3,195 Chinese patients with neurodevelopmental disorders exposed RYR3 as one of the six novel candidate genes to preferentially contribute to ASD." (PMID 36875674, 2023). "Interestingly, targeted sequencing and integrative analysis of 3,195 Chinese probands with several neurodevelopmental disorders exposed novel candidate genes involved in ASD, including three with relevance to Ca2+ homeostasis, namely: RYR3 [discussed in the Section “2.1." (PMID 36875674, 2023).
RYR3 also shares sentences with these, for which no sentence is quoted: diabetes (3 papers); cardiovascular disease (2); colon cancer (2); alcohol dependence (1); Arrhythmia (1); autism (1); autoimmune thyroid disease (1); Autoimmunity (1); behavioural disorders (1); catecholaminergic polymorphic ventricular tachycardia (1); cocaine dependence (1); depression (1); developmental and epileptic encephalopathy (1); developmental delay (1); dyslexia (1); epilepsy syndrome (1); immune system disorder (1); King-Denborough syndrome (1); lung squamous cell carcinoma (1); muscular dystrophies (1); myasthenia gravis (1); neurodegenerative disease (1); obsessive-compulsive disorder (1); osteopetrosis (1); primary immunodeficiency (1); rhabdomyolysis-myalgia syndrome (1); testicular germ cell tumor (1); thyroid carcinoma (1).